IL4 (interleukin 4)
Diseases named in the same sentence as IL4 in open-access papers (continued):
Sharing a sentence is not in itself a finding about the gene and the disease.
tumor (continued). "M1 TAMs elicit a Th1 response that can induce tumor cell killing, whereas M2 TAMs are activated by IL-4 and IL-13 produced by Th2 cells, eosinophils, and basophils." (PMID 35008305, 2021). "It is also reported that IL-4 released from tumor cells and T cells induces cathepsin protease activity in TAMs to promote tumor invasion." (PMID 33968034, 2021). "Both IL-4 and IL-13, when in excess, have been connected with more aggressive cancers, enhanced metastasis, proliferation, and tumor growth." (PMID 34071442, 2021). "Mediators released by tumor-infiltrating lymphocytes, such as T helper 2 (Th2)-cell-derived IL-4 and regulatory T (Treg) cell, and tumor-cell-derived IL-10, VEGF-A, TGF-β, and PGE2 activate an immunosuppressive program in TAMs." (PMID 34638388, 2021). "Th2-related cytokines (IL-4 and IL-13) regulate M2-like macrophages polarization which play a role in promoting tumor progression by creating an immunosuppressive environment." (PMID 34194433, 2021). "The effect of culture supernatants from unstimulated, LPS-stimulated, or IL-4-stimulated macrophages treated with compound 1 on the metabolic viability of solid-derived tumor cell lines was also investigated." (PMID 34207168, 2021). "Alternatively, TAMs can produce IL-4 and IL-13 influencing a Th2 lymphocytes response, promoting tumor growth." (PMID 34341329, 2021). "Reports have shown that PD-L1 in T cells can be induced in response to antigen presentation and sterile inflammatory cues (e.g., IFN-γ, IL-4), whereas PD-L1+ T cells can lead to tumor-promoting tolerance." (PMID 33320839, 2021). "Conversely, M2 macrophages are stimulated by the type 2 T helper cell (Th2) cytokines (IL-4, IL-10, and IL-13) and exhibit pro-tumorigenic functions, including tissue remodeling and tumor progression." (PMID 33916915, 2021). "For instance, Th2 lymphocyte-derived IL-4 and IL-13 can enhance epidermal growth factor expression in TAMs, which promotes tumor cell metastasis, as well as the suppressive activity of TAMs, which blunts CD8+ T-cell responses to therapy." (PMID 34603327, 2021). "In the MMTV-PyMT mice, the levels of type 2 inflammation cytokines such as IL-4 (PE) and IL-13 (serum) increased with tumor progression." (PMID 34707103, 2021). "M2 macrophages are induced by IL4 and promote a Th2 immune response and tumor growth and progression." (PMID 34685762, 2021). "IL-4 and IL-13 are also involved in the crosstalk with the tumor microenvironment (TME) by activating tumor-associated macrophages and myeloid-derived suppressor cells, which have tumor promoting functions." (PMID 33450900, 2021). "Considering aging as a potential confounder for tumor microenvironment, elder mice should be used to verify the effect of IL-4 on bone metastasis of CRC in further study." (PMID 34863091, 2021). "Reducing the IFNγ production by T Helper 1 and enhancing IL-4 secretion via T Helper 2 minimizes anti-tumor immunity and the immune response." (PMID 33472580, 2021). "Regarding the functional molecules of ILC2s, PD-1high ILC2s in tumor tissues expressed much higher levels of IL4 and IL13 than did PD-1low ILC2s in terms of mRNA level." (PMID 34194433, 2021). "Functionally, PD-1high ILC2s from tumor tissues expressed higher levels of IL-4 and IL-13 regarding both mRNA and protein levels than PD-1low ILC2s." (PMID 34194433, 2021). "The arrest of the IL-4/IL-13 pathway by neutralizing IL-4 and IL-13 cytokines leads to inhibition of tumor-cell proliferation." (PMID 34948183, 2021). "Since IL4/IL4Rα signal was reported to regulate cell proliferation, we next analyzed the expression of IL4Rα in early OCPs during tumor microenvironment." (PMID 34863091, 2021). "As expected, IL-4 and IL-13 levels were highly increased in ILC2s from PBMCs (IL-4, P<0.0001; IL-13, P<0.0001) and tumor tissues (IL-4, P<0.0001; IL-13, P<0.0001) of NSCLC patients than in ILC2s from HD PBMCs." (PMID 34194433, 2021).
tumor (continued). "These co-cultures, as well as TAMs and tumor cells alone, were stimulated with IL-4 or an IFN-γ plus a Toll-like receptor (TLR) agonist (either LPS or ODN1826), or they were left unstimulated." (PMID 34205330, 2021). "Inhibition of XBP1 in TAMs downregulated the expression of pro-tumor cytokines, such as IL-4, IL-6, MMP2 and VEGFA." (PMID 34667145, 2021). "Th2 cells secrete interleukin (IL)-4 and IL-10, which recruit immunosuppressive cells to negatively regulate the Th1 anti-tumor response, and support tumor growth and metastasis." (PMID 33639614, 2021). "IL-4 regulates lymphocyte expansion and function and exhibits anti-tumor activity by promoting Gr-1+ granulocyte and CD8+ T cell maturation." (PMID 33668827, 2021). "An increased level of IL12p70 and IFN-γ, decreased levels of immunosuppressive IL-10 and IL-4, and elevated T-lymphocyte infiltration in tumor tissues in TEXomiR-treated mice do suggest that TEXomiR treatment elicits strong immunomodulatory effects." (PMID 33987190, 2021). "Tumor angiogenesis is strongly promoted by CAFs through the production of immunomodulatory and pro-angiogenic chemokines and cytokines like IL-4, IL-8, IL-6, TNF, CXCL12, TGFβ and VEGF." (PMID 33472580, 2021). "In a skin carcinogenesis model, VEGF-A expression on tumor cells with IL10 and IL4 secreted by tumor cells and macrophages, respectively, induced M2 polarization that promoted tumor growth." (PMID 34447383, 2021). "ARG1 is induced in tumour-infiltrating myeloid cells such as TAMs, MDSCs, and DCs through the secretion of tumour-derived factors and metabolites, including IL-4, IL-13, IL-6, M-CSF, GM-CSF, TGF-β, and cAMP." (PMID 34685679, 2021). "4αβ allows efficient IL-4-mediated enrichment of transduced cells, while fully preserving anti-tumor activity and type 1 polarity." (PMID 35028604, 2021). "Tumor-associated macrophages (TAMs) and CC-chemokine receptor 1 (CCR1)+ immature myeloid cells are responsible for the tumor invasion through IL-4-dependent secretion of matrix-degrading enzymes such as MMPs, cathepsins, and heparanase." (PMID 34220337, 2021). "Reversing the tumor growth dynamics in Havcr2fl/fl mice via anti-IL4 treatment has proven that TIM3 ablation enables an antigen-specific anti-tumor immunity." (PMID 34580280, 2021). "Secretion of IL-4 by Th2 cells would mediate transport of macrophages and eosinophils into tumor sites for anti-tumor actions, and this immune transfer function is the main mechanism for the Th2-mediated anti-tumor effect." (PMID 34497832, 2021). "Contrastingly, pro-tumour TAMs recruit more Treg cells and induce apoptosis in CTLs through IL-4 and IL-1052,53." (PMID 34732817, 2021). "Studies have shown that tumour-derived IL-4, IL-5, IL-6, IL-10, and IL-13 can stimulate TAM polarization towards TAM-M2." (PMID 34141479, 2021). "Locally in the TME, it was shown that TFH can induce FL cells to release the chemokines CCL17 and CCL22, which can in turn recruit Tregs and more IL-4-producing T cells to sustain tumor growth and immunosuppression." (PMID 35071240, 2021). "For instance, recent work has demonstrated that targeted knockdown of TGF-βRII expression on CD4+ T cells augments anti-tumour responses and vascular remodelling in an IL-4-dependent manner." (PMID 33401460, 2021). "Nevertheless, the density of M1 macrophages infiltrated into the tumor in colon cancer is much lower than that of TAMs, whose profile is favored by IL4Rα expression, as well as by IL-4 from tumor cells in the tumor microenvironment." (PMID 34681866, 2021). "By contrast, during tumor progression there is a subversion of macrophage functions, from M1 to M2, due to many factors, including the presence of IL-4 synthesized by CD4+ T cells and tumor cells and of tumor-derived GF such as CSF1 and GM-CSF." (PMID 33920505, 2021). "Components of the Th2-mediated immune response, such as IL-4 and eosinophils, can decrease tumor growth and initiate anti-tumor activity." (PMID 34359965, 2021).
tumor (continued). "Tumor-associated macrophages (TAMs) expressing M2 (alternatively activated)-like phenotype imitate type II T-helper cells that express interleukin (IL)-4, IL-5, IL-6, IL-13, and IL-10 to suppress anti-tumor immune response." (PMID 34831357, 2021). "In tumor biology, macrophages tend to differentiate into the M2 type rather than the tumor-killing M1 phenotype and produce cytokines such as IL-10, IL-4, and IL-13, which can promote tumor progression." (PMID 34148033, 2021). "Treg, Th1 cells, IL-4 score, and IL-8 score were the significantly differentially expressed terms in the tumor microenvironment of IRScluster1 to IRScluster3." (PMID 34777331, 2021). "It is also reported that IL-4 activates the growth of tumor cells through the inhibition of apoptosis." (PMID 34203928, 2021). "The Th2 cells produce IL-4 and IL-10 and inhibit the host immune system, hence having a role in promoting tumor growth." (PMID 35265097, 2021). "The cytokines IL-4, IL-5 and IL-13 secreted by Th2 cells have been found to facilitate tumor growth." (PMID 34722304, 2021). "Conversely, the M2 macrophages play an important role in cancer promotion, tumor growth, angiogenesis, and metastasis, through the secretion of cytokines including IL4, IL-10, and transforming growth factor (TGF)-β." (PMID 34867821, 2021). "On the other hand, M2 or alternatively activated macrophages are typically activated by IL-4, IL-13 and IL-10, express IL-10 and favor wound healing as well as tumor development by suppressing anti-tumor T cell responses." (PMID 33494181, 2021). "They develop in the bone marrow and traffic into solid tumors, where they accumulate mediated by factors such as GM-CSF, M-CSF, G-CSF, VEGF, IFNγ, IL-6, and IL-4, which are secreted by the tumor cells themselves or other cells of the TME." (PMID 34795675, 2021). "On the contrary, IL-4 has also been shown to inhibit tumor growth and progression in other tissues, such as kidney cancer, which was dependent on tumor-specific CD8+ T cells." (PMID 35008550, 2021). "Studies have revealed that IL-4 antibody neutralization enhances antitumour immunity and delays tumour progression." (PMID 34930387, 2021). "IL-4 has been shown to enhance the recruitment of precursor T-cells, thus enhancing the immune response against the tumor." (PMID 33668356, 2021). "A recent study found that in lung cancer, IL-4 secreted by M2-myeloid cells and tumor cells activate the STAT6 pathway and promote M2 polarization and tumor progress." (PMID 34925244, 2021). "M2 macrophages meanwhile exert an immunosuppressive phenotype, favoring tissue repair and tumor progression; they secrete anti-inflammatory cytokines such as IL-10, IL-13, and IL-4 along with expressing CD206." (PMID 34917263, 2021). "Under the same study, an experiment on C57BL/6 mice with lycopene (40 mg/kg) administered intraperitoneally for 3 days resulted in the reduction of tumor volume, weight, IL-4, IL-10, gene expression of DMNT3a and methylation levels of promoters (IRF1, IRF7)." (PMID 34202203, 2021). "IL-4 blockade also alters inflammation in the tumour microenvironment, reducing the generation of both immunosuppressive M2 macrophages and myeloid-derived suppressor cells and enhancing tumour-specific cytotoxic T lymphocytes." (PMID 34930387, 2021). "In the later stages of tumor progression, the tumor microenvironment becomes rich in growth factors and mediators such as IL-4, IL-10, and TGF-β, which mediate macrophage polarization and acquire the M2-like phenotype." (PMID 34283044, 2021). "During tumor development increased expression of interleukin-4 receptor (IL-4R) and elevated IL-4 levels were found in CRC." (PMID 35008550, 2021). "At the tumor site, a complex interplay occurs between TAM, malignant cells and stromal cells, in which stroma-derived and tumor-derived factors, such as IL4, IL-10, IL-13 and TGF-β, cause a shift towards M2 polarization." (PMID 34298810, 2021).
tumor (continued). "At the same time, IL-4 was decreased, indicating that fusion protein immunization activates T cells and further confirming the tumor suppression effect in vivo." (PMID 34358202, 2021). "IL-4/IL-13-polarized MDMs effectively suppressed ESO-T-cell-mediated killing of A375-A2-ESO tumor cells; this immunosuppressive effect was largely alleviated by phenelzine treatment during MDM polarization." (PMID 34112755, 2021). "Remarkably, we observed an increase in the expression of Ki67+ cells as well as in the percentage of TOX+ Ki67+ cells at the tumor stage compared with the plaque stage, and a strong positive correlation was also observed between Ki67 and IL-4 expression." (PMID 34220814, 2021). "Recent studies have also shown that Wnt ligands produced by cancer cells use β-catenin signaling to stimulate immunosuppressive TAMs that support tumor growth and metastasis, and to upregulate the production of anti-inflammatory IL-4 and TGFβ." (PMID 34566949, 2021). "Tumor-cell-derived IL-4 also mediated apoptosis resistance in primary human CC cells and the human CC cell line T84." (PMID 33450900, 2021). "Th1 cells secrete cytokines IFN-γ, TNF-α, IL-12, which play an essential role in tumor immunity, and IL-4, IL-6, and IL-10 are cytokines secreted by Th2 cells, which can inhibit the secretion of cytokines by Th1 cells and promote humoral immunity." (PMID 35071004, 2021). "CSF-1, CCL2, 3, 14, and IL-4 are common tumor-derived factors driving the recruitment, proliferation, and M2-polarization of MPs." (PMID 33418996, 2021). "Recent study has confirmed that M2 macrophages activated by CD4+T derived IL-4 are the main cell type in various tumor tissues including breast cancer and are involved in tumor progression." (PMID 34618681, 2021). "Tumour-promoting M2 macrophages are induced in tumours by specific cytokines including interleukin-4 (IL-4), IL-10, IL-13 and macrophage colony-stimulating factor (M-CSF)." (PMID 34062862, 2021). "Once established, tumor-derived factors drive macrophages towards an immunosuppressive phenotype mediated through IL-4, IL-10 and TGF-β release similar to reparative macrophages during injury repair." (PMID 33441138, 2021). "On the contrary, TAMs (M2-like) polarized by IL-4 and IL-13 play the opposite immunosuppression and pro-tumor function in the TME." (PMID 33738286, 2021). "This study demonstrated that 4/21 ICR activates the STAT3 pathway in response to IL-4 stimulation, promoting Th17-like polarization and tumor-targeted cytotoxicity of CAR-T cells in vitro." (PMID 34386015, 2021). "IL-4 and IL-13 can display a stimulating influence on tumor progression and metastasis through interactions with various cells in the TME including TAMs." (PMID 33804263, 2021). "As a tumor develops, the enrichment of IL-4 and IL-13 produced by tumor cells and CD4+ T cells in the TME results in the polarization of TAMs towards an immunosuppressive phenotype, that promotes tumor growth, malignancy, and metastasis." (PMID 34112755, 2021). "As a potential tumor activator, IL-4 has been considered to promote the polarization of the M2 phenotype, thereby further inducing tumor metastasis." (PMID 34149932, 2021). "On the other hand, a significant decrease in tumor-progressive cytokines, including IL-10 and IL-4, from spleen cells treated with TEX was identified in the TEXomiR group compared to both the TEX and PBS groups." (PMID 33987190, 2021). "A recent study showed that the specific targeting of TGFβ signaling in CD4 T cells, via a TGFBR2 coupled to a CD4 antibody induces an anti-tumor response mediated by IL-4 in a mouse breast cancer model." (PMID 33498483, 2021). "Conversely, M2 macrophages promote tumor development by producing anti-inflammatory cytokines, such as IL-4, IL-10, IL-13, and TGFβ, providing an immunosuppressive microenvironment that promotes tumor immune escape." (PMID 33406733, 2021).
tumor (continued). "Still, in rhabdomyosarcoma cells, another study showed that tumor cell progression seemed to be regulated by the interleukin-4 receptor (IL-4R)-dependent signaling pathway, highlighting the role of IL-4 in this common type of STS." (PMID 34359785, 2021). "M2 TAMs secrete pro-tumor factors (IL-4, IL-6, IL-10, IL-13, EGF, and VEGF), while tumor suppressor M1 TAMs express antitumor factors (IL-12, major histocompatibility complex (MHC) class II, and TNF-α)." (PMID 34341329, 2021). "IL-4 combined with CpG oligonucleotide activated tumor-specific Th1-type immune responses and suppressed the tumor growth in a subcutaneous tumor model of C57BL/6 (B6) mice." (PMID 33450900, 2021). "Alternatively, Th2 cells can contribute to tumor immune escape through production of IL-10 and IL-4, both of which inhibit the response of Th1 cell effectors, the verification response of inflammatory cells, antigen promotion, and T cell proliferation." (PMID 35082830, 2021). "During interaction between tumor cells and ATC, several pro-inflammatory cytokines (IFNγ, TNF-α, IL-4, and IL-2) are released in the tumor microenvironment resulting in immunomodulation of the tumor cells, with upregulation of PD-L1expression on their surface." (PMID 34689789, 2021). "Expression of IL-4 in the mouse CC cell line colon 26 inhibited tumor growth by inducing local tumor killing and systemic immunity in mice." (PMID 33450900, 2021). "In contrast, M2-like TAMs are induced by Th2 cytokines such as IL-4, IL-10, IL-13, and/or M-CSF, and can favor tumor growth and promote TME remodeling by producing growth factors, immunosuppressive factors, pro-angiogenic molecules, and proteases." (PMID 34603327, 2021). "TGFβ is one of the most important anti-inflammatory cytokines that augments the action of IL-4 in promoting an M2 pro-tumor phenotype in a MAPK dependent signaling manner." (PMID 34566949, 2021). "Decreased Tregs at the tumor site, increasing IFN-γ/IL-4 level; partial control of tumor progression." (PMID 33898309, 2021). "The impact of M(IL4) treatment on C. rodentium infectivity, colon histopathology, tumor number and size and tissue-specific inflammation was examined in these models." (PMID 34691050, 2021). "Mice inoculated with IL-4-producing tumor cells showed rejection and a long-lasting anti-tumor immunity." (PMID 33670758, 2021). "When fibroblasts from tumor stage lesions were co-culture with MyLa cells, IL4 and IL16 expression was increased, which is consistent with a malignant CTCL phenotype." (PMID 33941102, 2021). "Adoptive transfer of tumor-specific IL-4-producing cytotoxic CD8 T cells (Tc2) was also less effective in controlling tumor growth compared to IFNγ-producing CD8 T cells (Tc1)." (PMID 34177932, 2021). "Nevertheless, IL-4 was recently described to have anti-tumor functions through angiogenic-dependent properties." (PMID 33498483, 2021). "The activation of naive CD4+ T cells by DCs not only releases cytokines (IL-4, IL-12 and IFNγ) within the tumour microenvironment but also facilitates its own (CD4+ T cells) differentiation into Th1 cells." (PMID 32466214, 2020). "M2 macrophages alternatively induced by Th2 cytokines (IL-4 and IL-13) act as a powerhouse for tumor angiogenesis and metastasis, by displaying an immunosuppressive phenotype and secreting abundant pro-tumor cytokines." (PMID 32512803, 2020). "The IL-4 and IL-13 signaling mediate biological effects, such as tumor proliferation, cell survival, cell adhesion and metastasis." (PMID 33233582, 2020). "Colon CSCs secrete higher levels of interleukin 4, which promotes drug resistance and inhibits anti-tumor immune responses." (PMID 33233552, 2020). "Suramin was shown to block binding of IL-4 to its receptors on human tumor cells and IL-4-induced mitogenic response." (PMID 32076052, 2020).